NRXN2 (neurexin 2)
Description:
Neuronal cell surface protein that may be involved in cell recognition and cell adhesion. Neuronal cell surface protein that may be involved in cell recognition and cell adhesion. May mediate intracellular signaling.
Tractability: Small molecule: a structure with a bound ligand is known. Antibody: its Gene Ontology location is reachable by antibodies, with high confidence; UniProt places it where antibodies can reach, with medium confidence; UniProt predicts a signal peptide or a membrane-spanning region. PROTAC: its protein half-life has been measured.
Gene: Protein-coding gene on chromosome 11 (64,606,174 to 64,723,197, reverse strand). Ensembl gene ENSG00000110076.
Subcellular location: Presynaptic cell membrane
Pathways (Reactome):
Neuronal System: Neurexins and neuroligins
Gene Ontology:
Molecular function: calcium channel regulator activity; cell adhesion molecule binding; neuroligin family protein binding; transmembrane signaling receptor activity
Biological process: adult behavior; social behavior; vocal learning; vocalization behavior; chemical synaptic transmission; gephyrin clustering involved in postsynaptic density assembly; learning; nervous system development; neuroligin clustering involved in postsynaptic membrane assembly; neuron cell-cell adhesion; neurotransmitter secretion; postsynaptic density protein 95 clustering; postsynaptic membrane assembly; signal transduction; synapse assembly
Cellular component: plasma membrane; presynaptic active zone membrane; presynaptic membrane; trans-synaptic protein complex
Genetic constraint (gnomAD): Loss-of-function variants: 28 observed, 121.04 expected, observed/expected ratio (o/e) 0.23, 90% interval 0.17 to 0.32. The upper end of that interval is the gene's LOEUF score, 0.32, which puts it in group 1 of 6, group 1 being the genes least tolerant of losing a copy. Missense variants: 1,789 observed, 2,185.7 expected, observed/expected ratio (o/e) 0.82, 90% interval 0.79 to 0.85. Synonymous variants: 1,033 observed, 946.97 expected, observed/expected ratio (o/e) 1.09, 90% interval 1.04 to 1.15.
Gene-disease validity (ClinGen):
ClinGen rates the evidence that NRXN2 causes each of these diseases.
complex neurodevelopmental disorder (autosomal dominant): Limited. A disorder that involves more than one phenotype associated with the central nervous system, including but not limited to intellectual disability, autism, and seizures (epilepsy).
Homologues: Orthologues: chimpanzee NRXN2 (99% identical), macaque NRXN2 (99% identical), rat Nrxn2 (98% identical), mouse Nrxn2 (98% identical), dog NRXN2 (90% identical), guinea pig NRXN2 (89% identical), tropical clawed frog nrxn2 (72% identical), rabbit NRXN2 (52% identical), zebrafish NRXN2 (39% identical), Drosophila melanogaster Nrx-1 (34% identical). Paralogues in human: NRXN1 (61% identical), NRXN3 (61% identical), CNTNAP4 (19% identical), CNTNAP5 (19% identical), CNTNAP3 (19% identical), CNTNAP3B (18% identical), CNTNAP2 (18% identical), CNTNAP1 (17% identical), CUBN (10% identical), F8 (10% identical), F5 (10% identical), HEPHL1 (9% identical), and 23 more.